INS (insulin)
Diseases named in the same sentence as INS in open-access papers (continued):
Sharing a sentence is not in itself a finding about the gene and the disease.
cancer (continued). "For instance, although insulin is essential for the regulation of glucose homeostasis, hyperinsulinemia increases the risk of chronic diseases, including cancer." (PMID 40443827, 2024). "The review also concluded that use of insulin (and analogues) is associated with a 50% increase in total cancer risk, compared to other antihyperglycemic drugs; mixed results were obtained for sulfonylureas." (PMID 38492115, 2024). "Comparative analyses between insulin secretagogues and metformin consistently revealed a more favorable cancer risk profile for the latter." (PMID 39595655, 2024). "IR-A is often overexpressed in cancer and is linked to an increased risk of malignancies, whereas IR-B is typically found in insulin-sensitive tissues." (PMID 38731097, 2024). "Insulin resistance, a known cancer risk factor, leads to high insulin levels, known as hyperinsulinemia, occurring before the onset of type 2 diabetes." (PMID 38339271, 2024). "A recent study revealed that higher daily insulin doses are associated with an increased risk of cancer, even after adjusting for age and sex." (PMID 39359726, 2024). "Proteins and pathways primarily associated with insulin-activated IR-A were involved in cancer, stemness, and interferon signaling." (PMID 38331804, 2024). "Mounting evidence suggests that PCAND is a paraneoplastic phenomenon caused by paracrine factors secreted by cancer or stroma cells, some of which have been shown to impinge on β-cells and inhibit insulin secretion." (PMID 39516378, 2024). "Studies have shown that the long term use of insulin, in particular in individuals with Type 2 diabetes, has an increase in cancer risk." (PMID 39588310, 2024). "These adipokines can induce pathological alterations in insulin pathways and promote a pro-inflammatory state, both of which are linked to increased cancer risk." (PMID 39630839, 2024). "This interplay between insulin, glucose metabolism, and cancer risk underscores the importance of monitoring insulin therapy and metabolic health in cancer-prone populations." (PMID 39588310, 2024). "Some epidemiological studies have reported an elevated cancer risk in individuals using exogenous long-acting insulin for diabetes therapy." (PMID 38339407, 2024). "The involvement of insulin and its receptor in cancer development is underscored by the fact that elevated insulin levels can augment IGF-1 production, a factor linked to an increased risk of specific cancers." (PMID 39301314, 2024). "Regular PA and exercise are also associated with improved insulin sensitivity, which plays a crucial role in reducing cancer risk by influencing cell growth and proliferation." (PMID 38831183, 2024). "Physical activity reduces adipose tissue and correcting metabolic abnormalities, which has been shown to reduce plasma insulin and increase insulin sensitivity and glucose metabolism, thereby lowering the risk of certain cancers." (PMID 38489391, 2024). "Although correlational human data have associated elevated insulin levels with various cancer types, establishing a definitive cause-and-effect relationship for any specific cancer type remains elusive." (PMID 38339407, 2024). "Despite debates surrounding these findings, recent evidence suggests that the use of exogenous insulin is linked to a 20% higher risk of cancer, particularly for liver, pancreatic, bladder, and neurologic tumors." (PMID 38339407, 2024). "Observational studies reported the association of raw garlic consumption with improvements of important health outcomes, including cancer risk, cardiovascular disease, insulin homeostasis, and liver function." (PMID 39279902, 2024). "In conclusion, the relationship between T1D and cancer risk is intricate and influenced by various factors, including insulin dose, disease duration, and the complex interplay of metabolic pathways." (PMID 39359726, 2024). "On the other hand, these studies on insulin use and cancer risk have been criticized due to design flaws." (PMID 39434861, 2024).
cancer (continued). "Exercise has been shown to be one of the lifestyle factors that reduce the risk of developing cancer, leading to a biochemical response that subsequently lowers plasma insulin levels." (PMID 38339407, 2024). "Akt1 is the core kinase subunit of the insulin growth factor pathway and has been implicated in starvation resistance in a cancer study." (PMID 38895364, 2024). "An intriguing explanation of the link between T1D and cancers lies in the relationship between daily insulin dose and cancer risk." (PMID 39359726, 2024). "Abnormal glucose metabolism is associated with cancer cachexia and leads to altered metabolic states, such as elevated plasma glucose and insulin resistance." (PMID 39624846, 2024). "Although excessive amounts of iron are linked to heart disease, cancer, and reduced insulin sensitivity, iron is a necessary element for biological activity." (PMID 39606069, 2024). "The altered expression of IGFs increases insulin concentration and insulin resistance signaling, which represent the mechanism linked to the development of several cancers." (PMID 38785834, 2024). "Possible biological mechanisms of SGLT2I on reduction of cancer risk include reduction of glucose uptake of cancer cells, thereby increasing cell necrosis and reducing tumour growth, increased insulin sensitivity, and reduced chronic inflammation." (PMID 38856768, 2024). "Obesity is a risk factor for multiple cancer types and can be causally linked with several biological mechanisms involved in cancer development including changes in inflammation, sex hormone metabolism, and insulin and insulin-like growth factor signaling." (PMID 39561210, 2024). "Several studies proposed the link between high levels of serum C-peptide, a stable marker of insulin secretion, and high risk of various types of cancer including breast, colorectal, and postmenopausal endometrial cancers." (PMID 39410536, 2024). "Data from Taiwan’s National Health Insurance database, which encompassed over 8000 cancer cases in T2DM patients, demonstrated that insulin use was linked to the highest overall cancer risk, followed by glinides and SUs." (PMID 39595655, 2024). "Given the well-established cancer cells dependence on glucose and insulin availability, KDs is a valid strategy, in association with pharmacological treatment, to counteract cancer proliferation." (PMID 37405618, 2023). "A number of studies have confirmed its beneficial effects on, for example, glucose levels, insulin metabolism, BMI and waist circumference, or the potentially decreased risk of cardiovascular disease and cancer, especially in women." (PMID 36900975, 2023). "Although high insulin levels were linked to cancer development, insulin concentration at the tumor microenvironment has not yet been assessed." (PMID 37511575, 2023). "The beta-tumor cell-6 (β-TC-6) cell line is a mouse islet β-cancer cell line derived from a transgenic mouse expressing genes encoding insulin, glucagon and somatostatin; β-TC-6 cells are capable of secreting insulin in response to glucose." (PMID 36674599, 2023). "The Hedgehog signaling is frequently coupled with bioenergetics of various cancers, and is associated with the insulin-independent glucose uptake in muscle and brown adipose tissue in obese and diabetic patients." (PMID 37061531, 2023). "Our results support the ongoing clinical evaluation of STX-478 in PI3Kα-mutated cancers, which is expected to expand the therapeutic window and mitigate counterregulatory insulin release." (PMID 37623743, 2023). "Metformin mitigates the high insulin level associated with cancer cell proliferation and poor clinical outcomes." (PMID 36562831, 2023). "Insulin-resistant patients have a higher overall cancer risk due to the mitogenic effect of insulin, which enhances a signaling pathway that activates the transcription of molecules involved in the cell cycle and proliferation." (PMID 36766711, 2023).
cancer (continued). "As mentioned in the introduction of this article, impaired insulin status is associated with the risk or survival of many cancers." (PMID 36936171, 2023). "Insulin resistance in cancer patients is different from the one in type-2 diabetes mellitus, it is characterized by normal fasting glucose levels associated with any insulin level." (PMID 38067294, 2023). "The mitogenic stimulation induced by excessive insulin levels has been suggested to be a potential cause of diabetic complications and cancer progression." (PMID 37779149, 2023). "Physical activity has predominantly been associated with protective effects against various cancers due to its anti-inflammatory effects, improved insulin sensitivity, and modulation of sex hormone levels." (PMID 37763224, 2023). "Three mechanisms by which higher general adiposity can increase cancer risk have been extensively reported in the literature: sex hormonal metabolism, insulin and insulin‐like growth factors (IGF) signaling, and adipokine pathways." (PMID 37766588, 2023). "With the exhaustion of β cell function, insulin secretion depleted, followed by a decrease in cancer risk." (PMID 37308998, 2023). "The involvement of IGF2 in carcinogenesis depends on its ability to link high energy intake, increase cell proliferation, and suppress apoptosis to cancer risk, and this is likely the key mechanism bridging insulin resistance to cancer." (PMID 36672737, 2023). "In patients with cancer cachexia, insulin resistance has been linked with decreased glucose tolerance and insulin sensitivity, leading to a reduction in glucose uptake." (PMID 37217930, 2023). "Nevertheless, data coming from observational studies are still conflicting and inconclusive, since some authors observe an association between insulin therapy and increased cancer risk, while others failed to register any association." (PMID 38146457, 2023). "KEGG analysis indicated eight cuproptosis-related genes in cancer-associated pathways, such as insulin secretion, ECM-receptor interaction, and PI3K-Akt signaling pathway." (PMID 36714025, 2023). "Emerging evidence have suggested a potential relationship between cancer development and diets associated with glucose and insulin metabolism." (PMID 37346909, 2023). "Observational studies published in the 2000s suggested that insulin users had a higher risk of malignant neoplasms, particularly colon, breast, and pancreatic cancers." (PMID 37364149, 2023). "In a UK retrospective cohort of 62,809 patients, metformin monotherapy was associated with the lowest cancer risk, compared with insulin or sulfonylureas." (PMID 35455439, 2022). "A high GI diet requires insulin, and the insulin–IGF axis has been associated with increased cancer risk." (PMID 36048786, 2022). "The Cremona study at the 15th year of follow-up revealed that patients in the group with the highest quintile of serum insulin had a 62% higher risk of cancer mortality." (PMID 35328822, 2022). "Studies illustrated that carbohydrate intake is positively associated with cancer via insulin and the related hormone, IGF-1." (PMID 35672814, 2022). "These include the “Sphingolipid signaling pathway”, in which GBA2 participates, “Axon guidance” that is associated with neuronal function, as well as the “Insulin resistance” and “Proteoglycans in cancer”." (PMID 35277195, 2022). "One of the typical metabolic alterations present in almost all cancer patients is glucose tolerance which is often associated with decreased insulin sensitivity." (PMID 35441960, 2022). "The current study suggests that insulin, thyroid hormone, and cancer-associated microRNAs are potential therapeutic targets that should be explored by basic science studies to improve the function of the RV to match that of the LV." (PMID 36552341, 2022). "Since 2009, data from observational studies suggest an association between insulin use and cancer risk, but results are often conflicting and inconclusive." (PMID 35681699, 2022).
cancer (continued). "All of which have been associated with cancer pathogenesis due to their enhancement of circulating insulin levels." (PMID 35244142, 2022). "Further studies are required to extend our evaluation of the effects of insulin, thyroid hormone, ion channel blockers, and cancer-associated microRNAs on RV performance." (PMID 36552341, 2022). "Analyzing the effect of exercise on the liver in the cancer model was important because the liver tissue is closely associated with maintaining body weight, insulin sensitivity, and chronic inflammation." (PMID 35801156, 2022). "On the other hand, inactivating 4EBP1-EIF4E resulted in increased translation of genes involved in inositol phosphate metabolism and the phosphatidylinositol signaling system that is implicated in insulin signaling and cell migration in cancer cells." (PMID 35626002, 2022). "In this study, with fasting and post glucose load insulin data collected, we were able to identify the different associations between these insulin levels and cancer risk." (PMID 35256755, 2022). "Specifically, the hyperstimulation of IR and its interaction with circulating insulin is a hallmark of various cancers." (PMID 35335158, 2022). "Cohort studies and meta-analysis showed that insulin exposure is associated with an increased risk of cancer in the pancreas, liver, kidney, stomach, respiratory system, breast, and colon." (PMID 36033393, 2022). "Despite mechanistic uncertainties, considering the strong epidemiologic evidence in support of a pathogenic link between insulin and cancer, numerous in vivo preclinical studies have explored this possibility interventionally." (PMID 35244142, 2022). "In the IGT group alone, the log-transformed insulin AUC level during OGTT was significantly associated with the risk of cancer (aHR = 2.03, 95% CI 1.08–3.81, P = 0.03)." (PMID 35256755, 2022). "Non excess risk was observed risk for this cancer in T2DM insulin users, compared to the general population (IRR = 0.8, 95% CI 0.35, 1.8)." (PMID 35681699, 2022). "Elevated insulin levels have been associated with increased cancer risk and progression in epidemiological studies." (PMID 36589440, 2022). "So, the enhanced survival and proliferation caused by insulin are essential for the fibrotic microenvironment formation and the development of cancer cells." (PMID 35252207, 2022). "This auto-regulating loop is associated with the frequent deregulation of the insulin growth factor signalling pathway in cancer." (PMID 36499258, 2022). "Solute carrier family-2-member-4-gene (Slc2a4) encodes GLUT4, which functions as an insulin-regulated facilitative glucose transporter and has been identified as a promising therapeutic target for cancer." (PMID 35711425, 2022). "We investigated the association between several insulin sensitivity indices (ISIs) and cancer-mortality over 3.5 decades in a cohort of adult men and women." (PMID 35921366, 2022). "Increased insulin levels have been shown to induce mitogenic effects and lead to cancer risk by activating both the insulin receptor and the insulin-like growth factor 1 (IGF-1) receptor." (PMID 35270737, 2022). "Knocking out KRAS (the most common gene mutation in 95% PDA patients) in cancer cells even made insulin lose the ability to promote cancer cell viability, and insulin even turned to induced tumor cell dormancy in vitro experiments." (PMID 35252207, 2022). "Researchers have identified multiple cancer risk factors including adipokines, cytokines, insulin/insulin-like growth factor axis, and other cellular signal pathways." (PMID 35507914, 2022). "In cancer cell lines, HS-173 causes cell cycle arrest and apoptosis via the intrinsic pathway which has been linked to disruption of growth factor, insulin and TGFβ receptor signaling." (PMID 35873156, 2022). "A retrospective study showed that patients treated with insulin agents such as human insulin, aspart, lispro and glargine exhibited a dose-dependent increased risk of cancer development." (PMID 35222270, 2022).
cancer (continued). "Leptin, CRP, fasting insulin, and estradiol appear to mediate the effect of high BMI on cancer risk to different extents, with likely varying degrees of importance between cancers." (PMID 35048536, 2022). "Although there have been many studies investigating the association between insulin and cancer, research on BTC is still very sparse." (PMID 35933633, 2022). "It has also been seen that patients on insulin or insulin-secreting agents (e.g., sulphonylureas) are at a higher risk of developing cancer compared to patients on oral insulin-sensitizing agents, e.g., metformin or thiazolidinediones (TZDs)." (PMID 36295107, 2022). "The most enriched protein families were associated with protein phosphorylation and insulin signalling, both of which are recognised to be crucial molecular components for patient survival in various cancers." (PMID 36290362, 2022). "A systematic review published in 2013 showed a significant increase or decrease in cancer risk for insulin users, depending on cancer site." (PMID 35681699, 2022). "Stxbp4 plays a key role in insulin signaling and has oncogenic activity and implicated in different cancers." (PMID 35389339, 2022). "We aimed to investigate the association between IR surrogates, i.e., fasting insulin, fasting plasma glucose levels and several ISIs, with cancer mortality, in a cohort of adult healthy men and women over a 40-year follow-up." (PMID 35921366, 2022). "Elevated circulating insulin/IGF1 levels and the upregulation of insulin/IGF receptor signaling have been implicated in the development of various cancers." (PMID 36142321, 2022). "One noteworthy finding of this study was the significant association patterns of the 21-gene RS and the individual cancer-related genes with specific metabolic factors and biomarkers of insulin and the IGF1 axis." (PMID 34456877, 2021). "Nevertheless, many data, mainly from observational studies (randomized clinical trials are usually too short to draw firm conclusions on the risk of cancer), indicate the protective effect of metformin and the pro-oncogenic effect of exogenous insulin." (PMID 33562380, 2021). "The association between insulin and cancer is based on the strong anabolic effect of hyperinsulinemia that leads to proliferative tissue abnormalities, stimulation of DNA synthesis, and cell proliferation." (PMID 33477996, 2021). "Active physical activity can not only reduce the risk of cancer by reducing weight but also reduce the cancer risk by reducing the level of insulin, IGF-1, IGF-binding protein 3 and leptin in the body." (PMID 35083251, 2021). "This relationship was independent of traditional CVD risk factors clustering with impaired insulin sensitivity as well as of cardiorenal complications and cancer, the risk of which has also been associated with IR." (PMID 33715620, 2021). "Subsequent studies have confirmed a higher incidence of cancer and a higher risk of death from cancer in people using insulin." (PMID 33562380, 2021). "PPAR signaling is associated with cancer and exerts pleiotropic functions in cancer, as PPARs regulate lipid metabolism and insulin production, and PPAR genes are aberrantly expressed during cancer development." (PMID 34646087, 2021). "Insulin, on the other hand, does increase malignant cell proliferation and invasiveness, but these effects are at least inconsistent regarding cancer risk and survival in patients." (PMID 33664364, 2021). "Increasing evidence suggested that the upregulated insulin was associated with tumorigenesis and cancer growth." (PMID 34488531, 2021). "The two most commonly studied antidiabetic drugs in relation to cancer risk are insulin and metformin, but some studies also investigated the effects of other drugs." (PMID 34356646, 2021). "Own study also showed elevated risk of cancer associated with insulin monotherapy, but it was attenuated to insignificant level when insulin was combined with metformin." (PMID 33562380, 2021).